TYMS (thymidylate synthetase)
Diseases named in the same sentence as TYMS in open-access papers (continued):
Sharing a sentence is not in itself a finding about the gene and the disease.
tumor (continued). "In addition, we demonstrate that TYMS inhibition in vivo by TYMS shRNA prolongs survival and reduces tumor incidence in hTS/Ink4a/Arf−/− mice." (PMID 37106126, 2023). "Moreover, a recent study revealed that the expression of TYMS is a frequent event in circulating tumor cells (CTC) of patients with advanced PCa." (PMID 36034466, 2022). "Specifically, NAA40 stimulates transcription of the one-carbon metabolic gene thymidylate synthase (TYMS), whose product is targeted by 5-fluorouracil (5-FU) and accordingly in primary CRC tumours NAA40 expression associates with TYMS levels and poorer 5-FU response." (PMID 34785778, 2022). "In addition to inhibiting TYMS, 5-FU can act by incorporating fluorinated derivatives into the RNA and DNA of tumour cells." (PMID 34132895, 2021). "We also identified E2F1-3 upregulation in SCLC as a potential driver of TYMS expression that may contribute to tumor aggressiveness." (PMID 32224870, 2020). "Thymidylate synthase (TYMS) is crucial for DNA synthesis in both normal and tumor cells." (PMID 31987036, 2020). "Notably, some genes related to exhaustion were also overexpressed in tumor‐infiltrating Tregs including TYMS, KIAA0101, CXCL13, CD27, HLA‐DQB1, HLA‐DMA, ENTPD1, CD200, DUSP4, and ZBED2." (PMID 32659053, 2020). "We hypothesized that genetic polymorphisms could perturb the TYMS mRNA-antisense mRNA autoregulatory complex by either increasing TYMS or decreasing ENOSF1 gene expression to promote uncontrolled DNA synthesis and tumor growth." (PMID 30134598, 2018). "Previous studies that have associated the expression levels of TYMS and tumor response to 5-FU have been controversial, and currently, TYMS expression is not used as a biomarker in clinical decision-making." (PMID 29026541, 2017). "It is thus tempting to speculate that the detection of ischemic areas within tumor tissues might represent a more reliable marker of resistance to 5FU treatment than increased TYMS or TK expression levels." (PMID 27965457, 2017). "Lower levels of tumor TYMS expression correlate well with improved response to fluoropyrimidines." (PMID 27774364, 2016). "TYMS overexpression in tumor cells correlated with a reduced response to pemetrexed-containing chemotherapy and might be used as a predictive biomarker in advanced NSCLC patients." (PMID 26502926, 2015). "Our study offers evidence in support of using qPCR to determine TYMS mRNA expression as an alternative to the standard evaluation of protein expression (i.e., IHC), provided at least 80 % tumor cell content per sample is achieved by laser capture microdissection." (PMID 26502926, 2015). "When the two additional loci in the TYMS genes (rs34743033 and rs34489327) were assessed for their potential association with tumor response (PR vs SD), the results did not indicate any statistically significant association." (PMID 25232828, 2014). "Therefore, the association between ERCC1, TYMS, RRM1, TUBB3 and TOP2A expression levels with the pathogenesis and development of ESCC was investigated using a clustered analysis in terms of tumor invasion and lymphatic and distal metastasis." (PMID 24926347, 2014). "The level of TYMS expression is known to be related to the response of tumor cells to 5-FU." (PMID 23915286, 2013). "Patients with triple repeats of this sequence (TYMS 3/3) had poorer tumor responses than those with shorter sequences (2/2 or 2/3), suggesting that germline analysis for genetic variants may assist in predicting response." (PMID 24455740, 2013). "We therefore investigated the expression of TYMS in the tumours." (PMID 22926706, 2012). "The non‐responsiveness to 5‐FU therapy in MSI patients might be related to higher expression of TYMS in these tumours." (PMID 22926706, 2012). "Its overexpression may confer to chemotherapy resistance and poor prognosis in other tumours, and recently TYMS has been regarded as an oncogene." (PMID 19662092, 2009).
tumor (continued). "One strength of our investigation is the simultaneous evaluation of an index of drug exposure (5FU CL) and of several TYMS and MTHFR polymorphisms possibly related to tumour sensitivity, in a group of patients homogeneously treated with a repeated bolus regimen." (PMID 19384296, 2009). "Importantly, circadian BMAL1 expression was in tumour of a mouse model followed by TYMS expression and combined overexpression correlated to low response and worse survival on 5-Fu treatment." (PMID 19662092, 2009). "Biologically, the prominence of anti-AGR2 suggests that immune recognition of AGR2-expressing tumor cells reflects ER stress-related neoantigen exposure, whereas anti-TYMS responses may correspond to proliferative or DNA repair-linked antigenicity characteristic of early neoplastic transformation." (PMID 41562247, 2026). "Hence, TYMS-targeted therapy may foster translational autoregulation, enhancing TYMS levels by two to four times, enabling tumour cells to avoid harmful effects." (PMID 40270992, 2025). "Furthermore, differences in study cohorts regarding relevant covariates known to be associated with TYMS expression (e.g., MSI, tumor stages, tumor location) may contribute to these inconsistencies." (PMID 39998667, 2025). "Additionally, high TYMS expression correlated with tumor size and N staging." (PMID 39744483, 2025). "However, the suppression of TYMS alone may produce effects that depend on the tumor’s epithelial–mesenchymal transition (EMT) state." (PMID 40075750, 2025). "Tumour periphery showed elevated acetate levels and enrichment in lipid metabolic pathways genes especially in luminal B. Furthermore, serine was increased in the periphery and higher expression of thymidylate synthase (TYMS) indicated one‐carbon metabolism increased in tumour periphery." (PMID 38332687, 2024). "Although thymidylate synthase (TYMS) inhibitors have served as components of chemotherapy regimens, the currently available inhibitors induce TYMS overexpression or alter folate transport/metabolism feedback pathways that tumor cells exploit for drug resistance, limiting overall benefit." (PMID 37097751, 2023). "Therefore, instead of high TYMS levels arising as a secondary response to increase tumor growth rates, we observed that high TYMS levels may be directly driving the increase in tumor growth, tissue invasiveness and metastasis." (PMID 37106126, 2023). "Hence, we hypothesized that if we reduce TYMS levels, we would sensitize tumor cells to respond to lower doses of pemetrexed or gemcitabine that were otherwise ineffective in the presence of elevated TYMS commonly detected in clinical patient samples." (PMID 37106126, 2023). "Compared with the presurgical levels, serum levels of TYMS-AAb, IGFBP5-AAb, and HAPLN1-AAb decrease at 3 months after surgery and remain low up to one year, implying a possibility of utilizing CMT-associated AAbs for predicting tumor recurrence or treatment responses." (PMID 36139323, 2022). "Thus, we further hypothesized whether KIF4A and TYMS might be considered as the tumor marker in the diagnosis of early OC." (PMID 31987036, 2020). "Furthermore, TYMS expression level decreased with respect to younger age and advanced tumor stage." (PMID 33046972, 2020). "Furthermore tumour samples with high TYMS levels are more likely to be resistant to 5-FU11." (PMID 30728402, 2019). "Specifically, TFRC, PLK1, TYMS, and TSSK6 were remarkably upregulated in tumor tissues compared to normal controls (P < 0.0001)." (PMID 40496862, 2025). "In contrast, tumor promoters such as MYBL2, TYMS, MYC, MCM7, and EGFL7 were downregulated in EF-24–treated cells." (PMID 40986633, 2025). "The expression levels of TFRC, LAMC1, PLK1, TYMS, and TSSK6 were significantly higher in tumor tissues while TNFSF14 exhibited higher expression levels in normal tissues." (PMID 40496862, 2025).
tumor (continued). "Our data clearly showed more pronounced upregulation (CRC tissue compared to normal tissue) of TYMS in patients with MSI tumors compared to patients with MSS tumors, even after taking the location of the tumor into account." (PMID 41440189, 2025). "Studies have shown that the expression levels of thymidylate synthase (TYMS) and TYMP in tumor tissues are significantly higher than in adjacent normal tissues." (PMID 40303404, 2025). "This metabolism enrichment highlighted enzymes at the interface between glycolysis (GAPDH, ENO1, LDHA) and one-carbon metabolism (TYMS, SHMT2, MTHFR, MTHFD1), further confirming the importance of these two pathways in CIMP tumours." (PMID 38540202, 2024). "A small number of genes were found significantly differentially expressed in HPV-positive versus HPV-negative tumours (for example NEFH, ZFR2, TAF7L, ZNF541, and TYMS)." (PMID 38643268, 2024). "As a result, the overexpression of MTHFD2 or TYMS significantly enhanced the tumor cell proliferation rate, whereas the tumor cell growth promoted by MTHFD2 or TYMS overexpression was decreased by the overexpression of MTR." (PMID 39039072, 2024). "For this purpose, we transfected the MTHFD2, TYMS, and MTR overexpression or knockdown vectors into the PRKDC-overexpressing HMCB cell line (PRKDC-OE-HMCB), respectively, and exanimated the tumor cell proliferation rates." (PMID 39039072, 2024). "5-FU is a inhibitor of thymidylate synthase (TYMS), a key enzyme in folate metabolism, and directly suppress the proliferation of tumor cells." (PMID 39513106, 2024). "We further evaluated the impacts of MTHFD2, TYMS, and MTR on tumor cell proliferation under PRKDC overexpression conditions." (PMID 39039072, 2024). "We utilized the CCK-8 assay to investigate how alterations in MTHFD2, TYMS, and MTR affect tumor cell growth." (PMID 39039072, 2024). "A four-gene signature, consisting of TYMS, GAPDH, TK1, and DHFR, was enough to diagnose the CIMP phenotype and identify tumours eligible for immunotherapy." (PMID 38540202, 2024). "Compared to the control group after 48 h of treatment with TGT, the expression of genes JUN, TYMS, HSP90AA1, HDAC1, CDK1, and ESR1 was downregulated, which showed inhibitory effect on tumor cell proliferation." (PMID 38297292, 2024). "The present study was to clear the biological roles and carcinogenic mechanism of TYMS in ESCC, and explored the possibility to use TYMS as a tumor marker in diagnosis and a drug target for the treatment of ESCC." (PMID 37682862, 2023). "The evaluation of thymidylate synthase (TYMS) and RAD23 homolog B (RAD23B) expression in circulating tumor cells (CTCs) provides complementary clinical information." (PMID 34207124, 2021). "For example, the smaller cell cluster B4b was a highly proliferative tumor with cells at either the G2/M, or S phase and displayed high expression of MKI67, CDK4, and other proliferative markers such as PCNA, TK1, and TYMS." (PMID 34001881, 2021). "Thus, in some tumours, 5-FU treatment may induce drug resistance by upregulating TYMS." (PMID 34132895, 2021). "Knockdown of TK1, TYMS and DTYMK reduced capability of forming tumor spheroids as shown in results of microscopy and in assays of 2 serial passages." (PMID 29100421, 2017). "we found that expression of TK1, TYMS and DTYMK enhanced tumor sphere formation capability and increased ALDH1 positive populations in well-differentiated HCC cells." (PMID 29100421, 2017). "As control, the coefficient of determination was also calculated for the reference genes and tumor markers CDK6 and TYMS and showed considerably low correlations between them." (PMID 27802291, 2016). "As a proof of concept, we tested the effect of BPTES-induced GLS1 inhibition combined with 5-FU-induced TYMS inhibition and showed that NSCLC cell growth was abrogated and that cell death was induced with significant reduction of tumour growth." (PMID 27929535, 2016).
tumor (continued). "As control, correlation of potential reference gene and suspected tumor markers (CDK6 and TYMS) was performed revealing very low R2-values, as expected." (PMID 27802291, 2016). "In our cohort, 50% of CIMP-High tumours showed a defect in the MMR system and 72% of dMMR tumours exhibited a high TYMS level." (PMID 23446022, 2013). "Only five resistance proteins (MDR1, TYMS, GSTP1, MGMT, MVP/LRP) were increased in comparison to sensitive tumours, while the other resistance factors revealed only marginal changes." (PMID 12177790, 2002). "Survival analysis revealed that patients with negative TYMS staining in their tumor tissues had longer overall survival times than patients with positive TYMS staining (p=0.038)." (PMID 40642061, 2025). "Analysis of B- and plasma cells (26,156 cells) showed that germinal centre (GC) B-cells (RGS13+, NEIL1+), cycling B-cells (UBE2C+, TYMS+) and naïve B-cells (TCL1A+, IL4R+) were all enriched in HPV+ve tumours compared to HPV-ve tumours, while switched B-cell subsets were found in both." (PMID 39757146, 2025). "Strong immunoreactivity of TFRC, LAMC1, PLK1, and TYMS was observed in tumor tissues, whereas weak or no staining was observed in normal tissues." (PMID 40496862, 2025). "Independent of other covariates, TYMS expression in tumor tissue, pT4 tumors, and emergency surgery were found to be of relevance for TTR." (PMID 39998667, 2025). "The expression of ABCC3, AMT and PCFT (p < 0.0001) was higher in mucosa compared to the tumor tissue, whereas the expression of FPGS (p < 0.0001), GGH (p < 0.0001), MFT (p < 0.01), RFC-1 (p < 0.0001) and TYMS (p < 0.0001) was lower in mucosa compared to the tumor tissue." (PMID 39998667, 2025). "Pemetrexed is a multitargeted antifolate that can be easily administered to patients and it shows antitumor activity in a wide range of tumor types whereas gemcitabine does not directly interact with TYMS." (PMID 37106126, 2023). "Also for miR-375-3p there is a miRNA response element in the 3’UTR of TYMS mRNA and overexpression of miR-375 mimics in CRC cell lines increased their sensitivity to cytotoxic activity of 5FU in vitro and in tumor-bearing mice." (PMID 35922756, 2022). "Ratios of the three AAbs, in particular IGFBP5-AAb and HAPLN1-AAb, noticeably declined at 3 and 12 months after tumor resection (respectively), albeit the reduction in the ratio of TYMS-AAb was not statistically significant." (PMID 36139323, 2022). "Levels of TYMS-AAb, IGFBP5-AAb, and HAPLN1-AAb all declined after tumor resection." (PMID 36139323, 2022). "Experiments showed the specificity of delivery of the conjugate to tumor cells and the suppression of cell growth with no TYMS de novo expression." (PMID 35053254, 2022). "Previous studies indicated that overexpression of thymidylate synthetase (TYMS) could suppress DNA synthesis and affect DNA methylation patterns, thus supporting cell proliferation, invasion, and tumor progression." (PMID 36248377, 2022). "GYP significantly reduced the expression of STAT3, EGFR, TYMS and MAPK14 in tumor tissues, while cisplatin combined with GYP could further reduce the expression of STAT3, TYMS and MAPK14 in tumor tissues." (PMID 36532716, 2022). "Isorhamnetin, kaempferol, FA, calycosin, hederagenin might play an anti-tumor role through targeting AKT1, CDK1 TYMS, MAPK3, AR, respectively." (PMID 34955857, 2021). "For example, the smaller cell cluster B4b was a highly proliferative tumor with cells at either the G2/M, or S phase (right two panels) and displayed high expression of MKI67, CDK4, and other proliferative markers such as PCNA, TK1, and TYMS." (PMID 34001881, 2021). "This phenomenon may constitute an underexplored mechanism of chemoresistance in tumor cells under EMT, implying that expression of the genes DPYD, TYMS, MTHFR, ERCC1, ERCC2, XRCC1, and GSTP1 may be modulated EMT-TFs." (PMID 33429840, 2021).
tumor (continued). "In a preliminary study with 30 patients, we showed that thymidylate synthase (TYMS) and RAD23 homolog B (RAD-23B) expression in CTCs before and after NCRT could predict tumor response in LARC patients." (PMID 34207124, 2021). "It is plausible that TYMS overexpression is the negative feedback response of tumor cells to overcome the competitive inhibitory binding of FdUMP as the active substrate of 5-FU." (PMID 34571731, 2021). "Genotyping of TYMS (5′TRP and 3′UTR), UGT1A1*28, UGT1A9*22 and UGT1A7*3 in metastatic CRC patients treated with irinotecan/5FU shows that the TYMS 3TRP/3TRP genotype is the only independent predictor of tumor response." (PMID 34948113, 2021). "In the setting of advanced CRC, TYMS protein levels in the primary tumor tissue did not predict the response to 5-FU in a metastatic disease site." (PMID 32933095, 2020). "Thymidylate synthase (TYMS) is a crucial enzyme for DNA synthesis in both normal and tumor cells." (PMID 30134598, 2018). "There is an expanding corpus of reports about TYMS expression levels in NSCLC patients, some confirming that TYMS expression is significantly increased in tumor cells but not in normal epithelial cells." (PMID 26502926, 2015). "In particular, this study suggests that patients with high TYMS levels and CIMP-High status may derive benefit from adjuvant therapy, which however should be avoided in those showing dMMR and low TYMS tumours." (PMID 23446022, 2013). "Mucinous tumours significantly overexpressed both TYMS and GSTP1 relative to nonmucinous tumours and patient-matched normal mucosa." (PMID 15655543, 2005). "Among the 5-FU metabolism genes, TYMS was significantly more upregulated in MSI CRC than in MSS tumors, (FC = 1.65, 95% CI 1.27–2.13 in patients with MSI tumors vs. FC 1.19 95% CI 1.02–1.39 in patients with MSS tumor; ANOVA interaction p = 1.01 × 10−6) even after adjustment for tumor location." (PMID 41440189, 2025). "This analysis confirmed the association of TYMS, TK1, SHMT2, MTHFD2, and DHFR expressions with the main prognosis markers (hypermutation, MSI, iCluster, expression subtype, and tumour stage) while MTHFD1, and not MTHFD2, was more strongly associated with methylation status." (PMID 38540202, 2024). "Additionally, ectopic overexpression of TYMS in murine NIH 3T3 cells exhibits oncogene-like activity by inducing parameters of the neoplastic phenotype, including foci formation, anchor-independent growth, and tumor formation in nude mice." (PMID 37097751, 2023). "However, surprisingly, a minor, non-significant increase of the expression TYMS gene, which has been associated with resistance to 5FU treatment, was only detectable in 3D1 MCTS, characterized by a relative sensitivity of tumor cells to 5FU." (PMID 27965457, 2017). "Furthermore, we observed MTHFD2 target engagement with TH9619 in vivo by performing CETSA on tumor samples, whereas no stabilization could be observed in the vehicle-treated animals, or those on TYMS with TH9619." (PMID 35228749, 2022). "Therefore, the expression and function of DPYD, TYMS, MTHFR, ERCC1, ERCC2, XRCC1, and GSTP1 may be influenced not only by genetic polymorphisms, but also by processes that are specific for the tumor tissue." (PMID 33429840, 2021). "Using RNA-sequencing data from The Cancer Genome Atlas, we observed a significantly higher expression of TYMS, TK-1, and SLC29A1 in tumor tissue (n = 371) than in adjacent nonmalignant tissue (n = 50; P < 0.05)." (PMID 32513905, 2020). "We have previously generated a genes signature induced by EGFR nuclear non-canonical activity, including two genes, TYMS and CCND1, upregulated by 5FU/CDDP chemotherapy in tumor cells." (PMID 33015030, 2020). "In the COID, the TYMS was not overexpressed, indicating that COID could be a potential tumor group for multifolate inhibitors." (PMID 25325012, 2014).
tumor (continued). "We then hypothesized that TYMS rs3786362 might have important effects on PFS and OS in mCRC patients and could be a predictive biomarker for survival of mCRC patients in subgroups of younger age, well and moderate tumor differentiation, with metastatic organism ≤ 2 and non-smoking status." (PMID 33046972, 2020).